CYP1A2 (cytochrome P450 family 1 subfamily A member 2)
Diseases named in the same sentence as CYP1A2 in open-access papers (continued):
Sharing a sentence is not in itself a finding about the gene and the disease.
autism (3 papers, 2020 to 2024). Persistent deficits in social interaction and communication and interaction as well as a markedly restricted repertoire of activity and interest as well as repetitive patterns of behavior. "In the CYP1A2 variant, two people (1 allergy-Hashimoto and one autism patient) carry the homozygous (AA) genotype, and two people (one allergy, one eczema) carry the heterozygous (AC) genotype." (PMID 39148948, 2024). "A significant decrease in CYP1A2 enzyme activities in children with autism was associated with significantly higher frequencies of three variant alleles CYP1A2*1C at SNP rs2069514, CYP1A2*4 at SNP rs72547516), and CYP1A2*6 at SNP rs28399424." (PMID 34502168, 2021). "However, persistent high melatonin levels could be caused by food or slow melatonin metabolism, itself perhaps caused by CYP1A2 gene polymorphism which might be associated with autism." (PMID 32477175, 2020). "This section summarizes the most recent human and experimental studies and evidence for the potential role of AhR and its regulated genes, CYP1A1, CYP1B1, and CYP1A2 on autism development." (PMID 34502168, 2021). "Further evidence supporting the role of CYP1A2 variations in ASD is the low urinary melatonin metabolite, 6-sulfatoxymelatonin, by CYP1A2 in mothers of children with autism compared to control mothers." (PMID 34502168, 2021). "What supports this possibility is that AhR and its regulated genes, CYP1A1, CYP1A2, and CYP1B1, are highly and constitutively expressed in the placenta, which may be activated by exposure to environmental toxicants during pregnancy and, hence, increase the incidence of autism." (PMID 34502168, 2021).
cholestasis (3 papers, 2019 to 2023). Impairment of the bile flow caused by obstruction within the liver, or outside the liver in the bile duct system. "Prior studies indicate that Cyp1a1, Cyp1a2, and Cyp2b1 are potential targets for treating of cholestasis." (PMID 37881184, 2023). "The genes regulated in all pathways, Cyp1a1, Cyp1a2, Cyp2a1, Cyp2b1, Cyp4a8, Cyp2c11, Rdh16, Alox15, Ephx2, Sult2a1, and Acox2, were the potential targets for ZYP treatment of cholestasis." (PMID 37881184, 2023).
Hepatitis (3 papers, 2004 to 2024). Inflammation of the liver. "Autoantibodies against CYP1A2 were found only in APECED patients with hepatitis whereas the presence of other autoantibodies was less specific." (PMID 31548517, 2017). "Hepatitis in APECED patients is associated with antibodies directed against CYP450 antigens CYP1A1, CYP1A2, CYP2A6 and CYP2B6." (PMID 31548517, 2017). "In cases of dihydralazine-induced hepatitis the production of anti-LM autoantibodies has been attributed to adduct formation of CYP1A2 with an activated metabolite of the drug." (PMID 15679907, 2004). "For instance, CYP1A2 is the molecular target in dihydralazine-induced hepatitis and AIH as a component of APECED, CYP2D6 in AIH-2 and in some patients with HCV infection, CYP2A6 in APECED and in a proportion of patients with HCV infection and UGT1 in some cases of AIH-2 and chronic hepatitis D or C." (PMID 15679907, 2004). "Mechanistically, rutaecarpine induces the CYP1A2 protein, which accelerates the metabolism of acetaminophen to produce a toxic intermediate, N-acetyl-p-benzoquinone imine (NAPQI), leading to severe liver inflammation." (PMID 39058167, 2024). "The major target autoantigen of anti-LM in both conditions (hepatitis as part of the APECED and drug-induced hepatitis) has been documented as the CYP1A2." (PMID 15679907, 2004).
Insulin resistance (3 papers, 2021 to 2024). Increased resistance towards insulin, that is, diminished effectiveness of insulin in reducing blood glucose levels. "High insulin resistance states could be associated with CYP1A2 induction and lower CLZ:NDMC ratios." (PMID 33479273, 2021).
liver cirrhosis (3 papers, 2013 to 2025). "The results led to the assumption of pharmacokinetic alteration of tizanidine in patients with liver cirrhosis due to impaired activity of CYP1A2." (PMID 33404754, 2021). "However, when co-administered with drugs like ciprofloxacin or under conditions such as liver cirrhosis that inhibit CYP1A2 activity, significant hypotension can occur." (PMID 40520522, 2025). "At variance with CYP1A1, a significant level of CYP1A2 mRNA was present in uninduced healthy rats (about 500 times higher than that of CYP1A1), which decreased markedly with increasing severity of liver cirrhosis." (PMID 23626760, 2013). "The results of both Western blot and qPCR analyses also show that basal mRNA and protein expressions of CYP1A2 decrease significantly in cirrhotic rats in proportion to the severity of liver cirrhosis (by about 45 and 80% in non-ascitic and ascitic rats, respectively)." (PMID 23626760, 2013).
liver fibrosis (3 papers, 2019 to 2024). "We found that the expression of CYP1A2 was inhibited in patients with liver fibrosis." (PMID 38287425, 2024). "However, the specific mechanism of CYP1A2 in liver fibrosis still requires additional investigation." (PMID 38287425, 2024). "The results of RT-PCR in liver tissue of rats with liver fibrosis showed that the expression of CYP1A2 and PCYT1A was up-regulated and the expression of CYP1B1 was down-regulated in AR treatment groups, which was consistent with the previously reported results." (PMID 31467589, 2019). "Metabolomics combined with network pharmacology was used for the first time to clarify that the treatment of AR on liver fibrosis, which is related to the regulation of arachidonic acid metabolism and ether lipid metabolism by modulating the expression of CYP1A2, CYP1B1 and PCYT1A." (PMID 31467589, 2019). "The mechanism of CBS, CYP1A2, FOXA1, GSTZ1, WDR72 and UHMK1 in the progression of liver fibrosis is still unclear." (PMID 38287425, 2024). "According to the validation of clinical specimens, CBS, CYP1A2, FOXA1, GSTZ1, WDR72 and UHMK1 were specifically expressed in patients with liver fibrosis or hepatocirrhosis." (PMID 38287425, 2024). "Taken together, our study found that AR could be involved in the regulation of arachidonic acid metabolism and ether lipid metabolism by regulating the expression of CYP1A2, PCYT1A and CYP1B1, thereby effectively improving liver fibrosis." (PMID 31467589, 2019).
migraine (3 papers, 2019 to 2025). "Furthermore, due to the limitations of the database, we are currently unable to clarify the role of CYP1A2 gene polymorphism in the relationship between caffeine intake and neurological disorders such as severe headaches or migraines in the adult population." (PMID 40438572, 2025). "Genetic variants in genes such as SLC6A4 (SERT), DRD2 (dopamine receptor), PRDM16 or CYP1A2, and GNB3 have been associated with a modified therapy outcome with triptans in migraine and cluster headache, respectively." (PMID 35222013, 2021).
pneumonia (3 papers, 2023 to 2025). An acute, acute and chronic, or chronic inflammation focally or diffusely affecting the lung parenchyma, caused by an infection in one or both of the lungs (by bacteria, viruses, fungi, or mycoplasma.). "The highestclozapine concentrations of Patient 1 were measured after she developed pneumonia.Infections have been associated with elevated clozapine serum levels, possibly viathe infection releasing cytokines that inhibit CYP1A2." (PMID 36703576, 2023). "Reduced activities of CYP2C19 and CYP1A2 were associated with a higher risk of pneumonia." (PMID 40731880, 2025).
Sepsis (3 papers, 2008 to 2025). Sepsis is defined as life-threatening organ dysfunction caused by a dysregulated host response to infection. "As shown in a cell culture sepsis model, downregulation of AhR results in a decreased CYP1A2 expression in hepatocytes." (PMID 38589754, 2024). "Sepsis and isoflurane have independently demonstrated an effect on reducing the hepatic CYP1A2-activity." (PMID 38589754, 2024). "The resulting cytokine-mediated decrease in CYP1A2 enzyme activity during sepsis was measured in vivo by two research groups." (PMID 38589754, 2024). "In the present study, we found that both isoflurane and sepsis were factors that independently decreased the CYP1A2-mediated methacetin metabolization as determined by the LiMAx test system." (PMID 38589754, 2024). "The presented data show that sepsis and isoflurane have independent and additive effects on reducing the hepatic CYP1A2-activity." (PMID 38589754, 2024). "The acute inflammatory cascade related to sepsis may adversely affect cytochrome P450 regulation, including CYP1A2 enzyme activity, and a prolonged reduction in enzyme function in patients recovering from critical illness may have contributed to the high peak concentrations." (PMID 18423009, 2008).
Stroke (3 papers, 2020 to 2023). Sudden impairment of blood flow to a part of the brain due to occlusion or rupture of an artery to the brain. "A study of a Chinese population, showed that Individuals with CYP1A2 rs762551 C was associated with a lower risk of stroke than that of allele A36." (PMID 37481659, 2023). "The specific mechanisms that link CYP1A2 variants to stroke occurrence still require further in-depth study in the future." (PMID 37481659, 2023). "By comparing with non-hypertensive cases, the correlation between CYP1A1 rs4646422, CYP1A2 (rs762551 and rs2470890) and stroke risk in hypertensive cases was first analyzed in the allele model." (PMID 33046100, 2020). "This study aimed to observe the relationship between CYP1A1 and CYP1A2 variants and stroke risk in the Chinese population." (PMID 33046100, 2020). "The chi-square test and logistic-regression analysis were used to explore the relationship between CYP1A1 and CYP1A2 variants and stroke risk." (PMID 33046100, 2020). "Individuals with CYP1A2 rs762551 C was associated with a lower risk of stroke than that of allele A. Age stratification analysis showed that rs762551 was only observed to be associated with a lower risk of stroke in ≤64ys age group." (PMID 33046100, 2020). "After age stratified by average age, the correlation between CYP1A2 rs762551 and stroke risk was analyzed." (PMID 33046100, 2020). "Then, molecular experiment is used to further verify the role of CYP1A1 and CYP1A2 polymorphisms in the course of stroke." (PMID 33046100, 2020). "This study investigated the association between CYP1A1 variants and CYP1A2 and stroke risk in the Chinese Han population." (PMID 33046100, 2020). "In this study, the results first showed that CYP1A1 and CYP1A2 variants were associated with stroke risk." (PMID 33046100, 2020). "Allele C of CYP1A2 rs762551 was associated with a lower risk of stroke than allele A (OR = 0.82, 95% CI: 0.68–0.99, P = 0.034)." (PMID 33046100, 2020). "CYP1A2 rs762551 influenced the risk of stroke among hypertensive patients." (PMID 34391463, 2021). "Additionally, there was a link between CYP1A2 rs762551 and stroke susceptibility in the codominant (adjusted OR = 1.65, 95% CI: 1.08–2.54, P = 0.022) and dominant (adjusted OR = 1.57, 95% CI: 1.04–2.36, P = 0.030) models." (PMID 33046100, 2020). "Moreover, CYP1A2 rs2470890 was associated with stroke risk in the codominant (adjusted OR = 1.91, 95% CI: 1.11–3.27, P = 0.019), dominant (adjusted OR = 1.85, 95% CI: 1.10–3.10, P = 0.021) and log-additive (adjusted OR = 1.67, 95% CI: 1.04–2.70, P = 0.035) models." (PMID 33046100, 2020). "Finally, the results only showed that polymorphisms of CYP1A1 and CYP1A2 were related to the risk of stroke, and there was no more clear mechanism study." (PMID 33046100, 2020). "Until now, the correlation between CYP1A2 variants and stroke risk has not been reported." (PMID 33046100, 2020). "However, the exact mechanism of CYP1A1 and CYP1A2 in stroke remains unclear." (PMID 33046100, 2020).
adenoma (2 papers, 2021 to 2025). A neoplasm arising from the epithelium. "Similarly, heterocyclic amines in well-done beef induce CYP1A2, a mechanism implicated in adenoma risk; individuals with high N-acetyltransferase-2 (NAT2) activity and high heterocyclic amine intake show increased risk compared with lower-intake groups." (PMID 41158125, 2025). "Two case-control studies have suggested that the combination of high CYP1A2 and high NAT2 activity is a risk factor for CRC or adenoma in individuals exposed to HAAs through the regular consumption of well-done meat." (PMID 34099058, 2021).
adenomyosis (2 papers, 2022 to 2023). The growth of endometrial tissue inside the muscular wall of the uterine corpus. "There is an increased frequency of the C allele in the T/C and C/C genotypes of the CYP1A1 gene, A allele in the C/A and A/A genotypes of the CYP1A2 gene, and the T allele in the C/T and C/C genotypes of the CYP19 gene in patients with adenomyosis." (PMID 37763670, 2023). "Patients with adenomyosis have increased frequency of the C allele in the T/C and C/C genotypes of the CYP1A1 gene, A allele in the C/A and A/A genotypes of the CYP1A2 gene, and the T allele in the C/T and C/C genotypes of the CYP19 gene compared with women without adenomyosis." (PMID 35887822, 2022).
anorexia nervosa (2 papers, 2020 to 2023). A disorder most often seen in adolescent females characterized by a refusal to maintain a minimally normal body weight, an intense fear of gaining weight, a disturbance in body image, and, in postmenarcheal females, the development of amenorrhea. "In this study, 24 patients with anorexia nervosa at two occasions ingested single oral doses of five test drugs known to be metabolized by CYP1A2, CYP2C9, CYP2C19, CYP2D6, and CYP3A4, respectively." (PMID 32529756, 2020). "Due to the lack of information on the possible effect of low body weight on most CYP enzymes, the aim of this study was to explore whether changes in body weight in patients with anorexia nervosa affect the metabolic activity of the CYP enzymes CYP1A2, CYP2C9, CYP2C19, CYP2D6, and CYP3A4." (PMID 32529756, 2020). "In conclusion, in patients with anorexia nervosa, the metabolic activity of CYP3A4 decreased, whereas the metabolic activity of CYP1A2 might increase, with increasing BMI." (PMID 32529756, 2020). "For CYP1A2, CYP2C9, CYP2C19, and CYP2D6, there are no studies on enzyme activities in anorexia nervosa or otherwise underweight subjects." (PMID 32529756, 2020). "Patients with anorexia nervosa have elevated concentrations of these cytokines, and if the increase in cytokine concentrations is sufficiently high to affect CYP enzyme activities, it could explain the possibly lower CYP1A2 activity, but not the increased CYP3A4 activity." (PMID 32529756, 2020).
atherosclerosis (2 papers, 2021 to 2024). A disease characterized by the build-up of fatty material and calcium deposition in the arterial wall resulting in partial or complete occlusion of the arterial lumen. "For example, overexpression of CYP7A1 seems to protect against atherosclerosis by reducing the accumulation of visceral fat among other factors, whereas downregulation of CYP1A2 has been correlated with the progression of HCC." (PMID 34262928, 2021).
Bradycardia (2 papers, 2024). A slower than normal heart rate (in adults, slower than 60 beats per minute). "A few cases of tizanidine-induced bradycardia with concomitant use of CYP1A2 inhibitors have been reported: one case each with loxoprofen, ticlopidine, lisinopril, and rofecoxib." (PMID 38894773, 2024). "Tizanidine-induced bradycardia has been documented in cases involving concurrent use of CYP1A2 inhibitors, occasionally leading to the requirement for a permanent pacemaker." (PMID 39493159, 2024). "Drug-induced bradycardia should be considered when starting tizanidine, even in the absence of comorbidities, structural cardiac disease, or concomitant use of CYP1A2 inhibitors." (PMID 38894773, 2024). "Concurrent use with CYP1A2 inhibitors may induce side effects even at standard dosages, and several cases of drug-induced bradycardia have been reported with concomitant use." (PMID 38894773, 2024). "However, reports of bradycardia occurring with a low dose of tizanidine (2 mg) in the absence of drug interactions, metabolic disorders, structural cardiac conditions, or abrupt cessation of smoking an action known to decrease CYP1A2 enzyme activity potentially are exceptionally uncommon." (PMID 39493159, 2024). "We report the case of a 37-year-old woman with tizanidine-induced bradycardia without concomitant CYP1A2 inhibitors and metabolic abnormalities or structural heart disease." (PMID 38894773, 2024).
congestive heart failure (2 papers, 2021). Failure of the heart to pump a sufficient amount of blood to meet the needs of the body tissues, resulting in tissue congestion and edema. "IL-6 was further shown to suppress CYP1A2, CYP2B6, and CYP3A4 mRNA levels and to be associated with inhibited CYP3A4, CYP1A2, and CYP2C19 functioning (but not CYP2E or CYP2D6) in patients with cancer, congestive heart failure, or post-surgery." (PMID 34071813, 2021). "In addition, one study showed that inflammatory markers were inversely correlated with CYP1A2 and CYP2C19 activity but not with CYP2D6 and CYP2E1 activity in patients with congestive heart failure." (PMID 34867341, 2021).
coronary heart disease (2 papers, 2020 to 2024). "Minor traits that were linked to CYP1A2 included serum albumin levels, red blood cell count, platelet distribution width, coronary heart disease, cardiovascular disease, brain morphology, and peak expiratory flow." (PMID 39457450, 2024).
endometrial cancer (2 papers, 2020 to 2022). Primary or metastatic malignant neoplasm involving the endometrium (mucous membrane that lines the endometrial cavity). "The CYP polymorphisms that we studied included CYP1A1 I462V and CYP1A1 T461N, as well as CYPIA2 D348N, CYP1A2 I386F, and CYP1A2 C406Y; the CYP1A1 polymorphisms were studied because their incidence is linked to lung, breast, and endometrial cancer." (PMID 32197424, 2020).
gout (2 papers, 2018 to 2022). A condition characterized by painful swelling of the joints, which is caused by deposition of urate crystals. "ABCG2, GCKR, MLXIPL, and cytochrome P450 family 1 subfamily A member 2 (CYP1A2) are variants associated with coffee consumption habits, and GCKR and ABCG2 are associated with low coffee intake and a high gout risk." (PMID 35813212, 2022). "Neither MLXIPL nor CYP1A2 were associated with gout, with multivariate adjusted OR 1.24 (95% CI 0.95–1.61, P = 0.11) and 1.16 (95% CI 0.96–1.40, P = 0.12), respectively." (PMID 29976226, 2018). "The urate-increasing GCKR and ABCG2 alleles were associated with gout (multivariate adjusted p < 5 × 10−8 for both), but the urate-increasing MLXIPL and CYP1A2 alleles were not." (PMID 29976226, 2018).
heart failure (2 papers, 2018 to 2024). Inability of the heart to pump blood at an adequate rate to meet tissue metabolic requirements. "Other risk factors associated with inadequate exposure (evaluated in only one study) were lower protein binding beta-lactams, CYP1A2 polymorphism for ciprofloxacin, heart failure, McCabe score, infusion duration, and high drainage fluid production for beta-lactams." (PMID 39334976, 2024).
liver dysfunction (2 papers, 2012 to 2013). "Since ethical constraints do not permit methodologically rigorous studies in humans, this question was addressed by investigating the effect of the prototypical inducer benzo[a]pyrene (BP) on CYP1A1 and CYP1A2 in cirrhotic rats stratified according to the severity of liver dysfunction." (PMID 23626760, 2013).
lung adenocarcinoma (2 papers, 2015 to 2024). A carcinoma that arises from the lung and is characterized by the presence of malignant glandular epithelial cells. "Some other research articles reported that the combined NAT2/CYP1A2 status was related to lung adenocarcinoma." (PMID 25915206, 2015).